RELB (RELB proto-oncogene, NF-kB subunit)
Diseases named in the same sentence as RELB in open-access papers (continued):
Sharing a sentence is not in itself a finding about the gene and the disease.
autoimmune disease (continued). "Across the T cell populations of these autoimmune diseases, CCR7, RELB, and IRF1 were notably highly expressed in JIA T cells, which revealed that CCR7+/RELB+/IRF1+ T cells independently response for JIA." (PMID 40406113, 2025). "Investigating the TFs regulating the fine‐mapped autoimmune disease enhancers, we find the known immune response TFs NFKB1/2, RELB and IRF8, but also MBD2, ZBT14 and PURA, which we identified as important TFs for predicting response to infection." (PMID 37073532, 2023). "Here, using mice carrying conditional ablation of RelB in T cells, we evaluated its role in the development of conventional CD4+ T (Tconv) cells and their function in autoimmune diseases." (PMID 34608221, 2021). "RelB−/− mice also have impaired negative selection, and T-cell-dependent multiorgan autoimmune disease." (PMID 29872433, 2018).
Autoimmunity (11 papers, 2016 to 2025). The occurrence of an immune reaction against the organism's own cells or tissues. "Genetic loss of the NF-κB subunit RelB in humans and mice leads to autoimmunity and lethal multi-organ inflammatory pathology." (PMID 39929805, 2025). "RelB-deficient mice have reduced thymic cellularity, markedly fewer mTECs, lack Aire expression, and suffer from autoimmunity." (PMID 38635416, 2024). "Several studies have implicated the loss of RelB in DCs as a key driver of autoimmunity in RelB−/− mice, demonstrating the sufficiency of either the absence or presence of RelB in DCs alone in promoting or suppressing the inflammatory pathology, respectively, in the lung, liver, spleen and thymus." (PMID 39929805, 2025). "It would therefore be interesting to determine whether this procedure can also correct organ-related autoimmunity in patients with AR partial RelB deficiency." (PMID 39231201, 2024). "However, it remains unclear which of these mechanisms is responsible for mediating autoimmunity in RelB-deficient patients and mice." (PMID 39929805, 2025). "NF-κB signaling via RelB suppresses type I IFN signaling in cDC2s while selective deletion of RelB in dendritic cells protects against autoimmunity." (PMID 37042831, 2023). "To directly assess the role of RelB in a murine model of T-cell mediated autoimmunity, we immunized control and mutant mice with MOG33-55 peptide to induce EAE." (PMID 34608221, 2021). "In contrast, the conditional deletion of RelB in Foxp3+ Tregs does not alter the number and function of this subset, even though the germline deletion of RelB induces autoimmunity and an expansion of Foxp3+ Tregs, mainly due to T cell-extrinsic mechanisms." (PMID 30364244, 2018). "NF-κB2 and RelB are important regulators of immune tolerance, as shown by germline deletion of the respective proteins in Relb−/− and Nfkb2−/− mice, which results in spontaneous autoimmunity." (PMID 35672519, 2022). "SS-like autoimmune lesions in the CCR7 KO and RelB KO mice occur through the impairment of T cell differentiation or selection in the thymus." (PMID 28587293, 2017). "Consistent with the critical mTEC-intrinsic role of p52/RelB heterodimers in establishing tolerance to type I IFNs, HSCT did not prevent the development of thymic stromal cell-dependent autoimmunity in P1, who developed auto-Abs against type I IFNs after transplantation." (PMID 39231201, 2024).
lymphoma (11 papers, 2012 to 2025). A malignant (clonal) proliferation of B- lymphocytes or T- lymphocytes which involves the lymph nodes, bone marrow and/or extranodal sites. "One other SNP, rs12609547, in RELB, was mildly associated with marginal zone lymphoma (OR: 2.03 [95% CI: 1.34–3.07], pG = 0.0015)." (PMID 24098683, 2013). "Finally, we analyzed whether RelB-deficient LMP1/CD40 mice still develop lymphomas." (PMID 36110848, 2022). "Differentially regulated genes were enriched for classical lymphoma driver genes downstream of the BCR, including MALT1 and CARD11, as well as NFATC2, TNFRSF13C (BAFF), and components of the NF-κB (RELB, IRAK1, BCL3, and TNFRSF1B) pathway." (PMID 39082968, 2024). "In lymphoma cells, knockout of GRK2 leads to enhanced MALT1-mediated IκB phosphorylation, RELB and CYLD cleavage, cytokine secretion, and cell proliferation, and GRK2 rescue reverses these effects." (PMID 34917606, 2021). "Further analysis of lymphoma development in these mice revealed that monoclonal B cell populations occurred earlier and with a higher incidence in LMP1/CD40 mice in comparison to LMP1/CD40//RelB-KO mice." (PMID 36110848, 2022). "In LMP1/CD40 mice, lymphoma incidence and expansion was reduced in the absence of RelB." (PMID 36110848, 2022). "Despite the limited availability for p52 ChIP-sequencing results, we were able to determine that in lymphoma cells, p52 has been shown to bind to multiple sites in the HIF-2α gene, however there is no documented binding of RelB to the HIF-2α gene." (PMID 30096845, 2018). "While CD40 is known to activate non-canonical NF-κB signaling component RelB, which has been shown to control BCLXL expression in related hematological malignancies, the control of MCL1 by specific NF-κB subunits is less clear, particular in the context of lymphoma." (PMID 40819126, 2025).
ovarian carcinoma (10 papers, 2015 to 2025). A malignant neoplasm originating from the surface ovarian epithelium. "Moreover, the loss of RELB in mouse xenograft models using ovarian cancer cell lines significantly decreased chemoresistance, tumorigenesis, and ALDH expression and activity." (PMID 35159096, 2022). "In previous works, we have delineated the roles of RELA and RELB in sustaining the ovarian cancer TIC stem-cell like population while showing that enhanced ALDH activity is a marker for TICs." (PMID 37175530, 2023). "We observed similar tumor suppressive characteristics of miR-335-5p across several ovarian cancer cell lines silenced for RELA/RELB." (PMID 37175530, 2023). "ALDH can be inhibited by silencing RelB, which indicates the significance of NF-κB activity in ovarian cancer." (PMID 36531159, 2022). "Preclinical models have shown decreased RelB expression with doxycycline treatment in ovarian cancer cells in addition to significantly decreased spheroid formation, possibly due to increased c-myc-cyclins D1 and E." (PMID 36531159, 2022). "Based on our current understanding of RELA/RELB signaling in promoting ovarian cancer proliferation and stem-cell phenotypes, the decreased expression of has-miR-452-5p when RELA or RELB are silenced across OV90, OVCAR8, and ACI23 cells suggests an oncogenic function." (PMID 37175530, 2023). "In addition, RelB in advanced ovarian cancers, supports tumor-initiating cells through the cancer stem-like associated enzyme aldehyde dehydrogenase (ALDH), and the loss of RelB leads to reversion of chemoresistance and inhibition of tumorigenesis in mouse xenograft models." (PMID 31586084, 2019). "In ovarian cancer, a lack of association of RelB expression and patient prognosis was reported." (PMID 26186215, 2015). "In support of an antitumor tumor immune response, by targeting intracellular PD-L1 with a cell-penetrating antibody, the mRNA expression of PDCD1LG2, BIRC3, RELB, and VSIR was significantly decreased in ovarian cancer cells." (PMID 39996786, 2025). "We also found a significant positive correlation between PD-L1 (CD274) and the PDCD1LG2, BIRC3, RELB, and VSIR genes in the TCGA ovarian cancer-patient database." (PMID 39996786, 2025). "Our previous study demonstrated that exogenous CCL2 promotes ovarian cancer cell proliferation by stimulating ERK signaling and regulating the JUN, RELB, and NF-κB2 expressions." (PMID 37445830, 2023). "The absence of RelB also decreased ovarian cancer tumor metastasis to abdominal organs." (PMID 36531159, 2022).
pancreatic cancer (9 papers, 2013 to 2026). "NIK is elevated in pancreatic cancer and associated with increased proliferation and up-regulation of RelB and p52 are associated with mutated KRAS pancreatic cancer with IKKα dependent gene expression being observed." (PMID 30347849, 2018). "This study provides critical insight into the regulatory dynamics of NF-κB signaling in pancreatic cancer and highlights the specialized functions of RELA and RELB in modulating gene expression and tumor-microenvironment interactions." (PMID 41844578, 2026). "In MIA PaCa-2 (a pancreatic cancer cell), LOX-PP attenuated the ERK and Akt activities and decreased the levels of the NF-Kβ p65 and RelB subunits and cyclin D1, which are activated by RAS signalling." (PMID 23750284, 2013). "In pancreatic cancer, EZH2 negatively regulates p27Kip1 expression in a RelB:p52-dependent manner." (PMID 31277415, 2019). "However, clonogenic survival was not affected by the knockout of RelB in pancreatic cancer cells, suggesting a minimal role in this differential response." (PMID 33923601, 2021).
glioblastoma (8 papers, 2013 to 2023). The most malignant astrocytic tumor (WHO grade IV). "Our analysis showed that high RelB expression in glioblastoma patients was associated with significantly shorter time to disease progression (∼10 months vs. 80 months), as well as almost 20% lower survival rates." (PMID 23451236, 2013). "The invasive nature of Glioblastoma Multiforme (GBM) cells has been reported to be associated with high RelB expression." (PMID 36899924, 2023). "Interestingly, while the YY1-RelA complex was shown to function as a transcriptional repressor, a complex between RelB and YY1 was shown to function as a transcriptional activator in glioblastoma multiforme (GBM) cells and promotes GBM growth." (PMID 31824839, 2019). "To further characterize gene expression in the Ad-GSCs and Sp-GSCs tumor xenografts, we examined the expression of genes previously defined to be characteristic of the Classical (FGFR3, PDFA, EGFR, AKT-2 and Nestin) and Mesenchymal (CHI3L1, TRADD, NF1, RelB and CASP4) glioblastoma subtypes." (PMID 25955030, 2015).
Immunodeficiency (8 papers, 2010 to 2025). Failure of the immune system to protect the body adequately from infection, due to the absence or insufficiency of some component process or substance. "In humans with RelB deficiency, patients suffer from severe immunodeficiency with shortage-specific antibodies due to the halted B cell development and the absent CD27+ memory B cells." (PMID 34521820, 2021). "The most frequent main genetic causes of cellular and humoral immunodeficiencies in children infected with SARS-CoV-2 were DOCK8 deficiency (n = 6), IL2RG (n = 5), RelB deficiency (n = 3), JAK3 deficiency (n = 3), and IL7Ra deficiency (n = 3)." (PMID 37559153, 2023). "RelB deficiency led to reduced T cell proliferations to mitogens and skewed T cell receptor (TCR) repertoire, together with impaired antibody responses, presenting combined immunodeficiency." (PMID 36180657, 2022).
Sepsis (8 papers, 2016 to 2025). Sepsis is defined as life-threatening organ dysfunction caused by a dysregulated host response to infection. "- E2 inhibits macrophage M2 polarization by suppressing nucleus translocation of RelB and its downstream gene expression in early stage of sepsis." (PMID 32793229, 2020). "We discovered that in cell and lean mouse models of sepsis that nuclear SIRT-1 couples with nuclear NFκB p65/ RelB, nuclear SIRT-6 and mitochondrial SIRT-3 as homeostasis checkpoints during acute sepsis-inflammation." (PMID 27500833, 2016). "Furthermore, RelB accumulated at the TNF-α promoter region in endotoxin-tolerant sepsis blood leukocytes." (PMID 30533222, 2018). "NF-κB transcription factor family members, including RELB, NFKB2, REL, and IRF1, predominantly control WARS1-induced gene expression networks, indicating recapitulating hyperinflammatory sepsis endotypes." (PMID 38177528, 2024). "RELB, NF‐κB1, and NF‐κB2, crucial in both classical and nonclassical NF‐κB pathways, were elevated, suggesting NF‐κB pathway activation in sepsis." (PMID 40779122, 2025). "In addition, nuclear SIRT1 can guide RELB to differentially induce SIRT3 expression, and it also can increase mitochondrial biogenesis, which alters bioenergetics during sepsis adaptation." (PMID 30533222, 2018).
viral infection (6 papers, 2018 to 2025). "Two out of the eight patients with autosomal-recessive RELB deficiency developed a severe viral disease (varicella pneumonia, n = 2; and PML, n = 1), and both had autoantibodies neutralizing IFNα and IFNω." (PMID 37938781, 2023). "has shown that following HSCT, patients with RELB defects may develop anti–type I interferon autoantibodies, predisposing them to life-threatening viral infections despite apparent immune reconstitution." (PMID 41280889, 2025). "Our study found that RelB plays a different role in the process of prototype foamy virus infection than other viruses." (PMID 32881382, 2020). "We next asked whether endogenous RelB has any effect on the transcription of HIV-1 during viral infection." (PMID 30241541, 2018). "Analyzing the results, we noted that RelB, a member of NF‐κB protein family, was significantly downregulated by PFV infection, while other four members of the family, such as relA, c‐rel, p50, and p52, did not detect significant changes in transcriptional level 24 h after virus infection." (PMID 32881382, 2020).
atherosclerosis (5 papers, 2007 to 2025). A disease characterized by the build-up of fatty material and calcium deposition in the arterial wall resulting in partial or complete occlusion of the arterial lumen. "Similarly to what observed with anti-US28 peptide antibodies, anti-UL122 antibodies induced up-regulation of transcription factors, in particular genes involved in NF-kB activation pathway such as TANK and RELB, which have been implicated in atherosclerosis." (PMID 17534423, 2007). "The present study has demonstrated the role of PARP in modulating inflammatory responses through assembly/disassembly of NF-κB subunits (IκBα with either RelA/p50 or RelB/p52) in monocytes/macrophages, major participants in the pathogenesis of atherosclerosis." (PMID 38335214, 2024).
chronic lymphocytic leukemia (5 papers, 2010 to 2023). "RELB has previously been identified as a sex‐discriminatory candidate gene in trichostatin A‐treated chronic lymphocytic leukaemia cells due to repressed expression in resistant male cells, but upregulation in resistant female cells." (PMID 34766125, 2020).
colorectal cancer (5 papers, 2015 to 2024). A primary or metastatic malignant neoplasm that affects the colon or rectum. "Interestingly, the association of RelB with TAK1 expression in our data may suggest that the alternative NFκB pathway is complicit in colorectal cancer pathogenesis, which is in keeping with the literature." (PMID 39068768, 2024). "LYL1 gene amplification was associated with the upregulation of cancer-related pathways in uterine corpus endometrial cancer, and RELB gene plays an oncogenic role in colorectal cancer." (PMID 34445498, 2021). "CSCs from MC38 colorectal cancer and MC38-derived tumors showed that THF inhibited CSC formation and induced apoptosis of MC38-derived CSCs through the c-Myc/BRD4/PD-L1/RelB/IL6 axis." (PMID 37924094, 2023). "However, the significance of RelB in colorectal cancer (CRC) remains unclear." (PMID 30473630, 2018).
COVID-19 (5 papers, 2021 to 2024). A disease caused by infection with severe acute respiratory syndrome coronavirus 2. "Levels of mRNA encoding various components of the NF-κB complex, including NF-κB1, NF-κB2, RELB, and IκBα, were significantly elevated in PBMCs from patients with severe or critical COVID-19." (PMID 37310504, 2023). "The proteins encoded by the ‘dark’ genes TRADD, FOS and DDGs RELB, JUN, IKBKG are involved in the MAPK signaling pathway, which is a potential signaling pathway for the spread and development of COVID-19." (PMID 37853311, 2023). "Intriguingly, within these networks, certain molecular entities (RELB, DDIT3, and FOSL1) were identified as hub genes with increased expression in our patient samples during the 1-year follow-up after severe COVID-19." (PMID 39205185, 2024).
lung adenocarcinoma (5 papers, 2015 to 2019). A carcinoma that arises from the lung and is characterized by the presence of malignant glandular epithelial cells. "While the relationship between RelB and a variety of tumors is widely studied, such as in laryngeal cancer, lung adenocarcinoma and colon cancer, the role of RelB in MS is still obscure." (PMID 31881915, 2019). "Recently, our studies have shown that RelB expression is present in lung adenocarcinoma and squamous cell carcinoma at different levels." (PMID 29983639, 2018). "For the first time, we have provided evidence that in vitro knockdown of RelB also suppresses the migration and invasion abilities of lung adenocarcinoma SPC-A1 cells." (PMID 29983639, 2018). "In in vitro assays, we found that RelB silencing affects lung adenocarcinoma SPC-A1 cell proliferation, which can be attributed to inhibited AKT activity." (PMID 29983639, 2018). "Nuclear factor (NF)-κB signalling is required for lung adenocarcinoma development in mice, and both of its subunits RelA and RelB were independently reported to be highly expressed in human non-small cell lung cancer (NSCLC)." (PMID 26147201, 2015). "However, unlike previous reports on other malignancies, RelB silencing did not interfere with the survival of lung adenocarcinoma SPC-A1 cells." (PMID 29983639, 2018).
non-small cell lung carcinoma (5 papers, 2015 to 2024). A group of at least three distinct histological types of lung cancer, including non-small cell squamous cell carcinoma, adenocarcinoma, and large cell carcinoma. "RelB is involved in the initiation, progression, and chemo-resistance of several solid tumors including prostate, breast, endometrium, bladder, laryngeal, and non-small cell lung cancer." (PMID 30473630, 2018). "However, the function of RelB in non-small cell lung cancer (NSCLC) is still unclear." (PMID 29983639, 2018). "In non-small cell lung cancer, a tumor type with high similarity to HNSCC, two previous studies identified similar roles for RelB as a potential biomarker of tumor progression and survival." (PMID 29371965, 2017).
rheumatoid arthritis (5 papers, 2005 to 2022). A chronic, systemic autoimmune disorder characterized by inflammation in the synovial membranes and articular surfaces. "Furthermore, in humans with rheumatoid arthritis (RA), cDC2 are decreased within the blood, but expanded within the lymph nodes, and the RA synovium is enriched with RelB+ DCs." (PMID 32194571, 2020). "In a rheumatoid arthritis mouse model, the IKKα-dependent non-canonical heterodimer relB-p52 enhances the transcriptional activity of NOTCH and Rbpj, required for the transcription of ADAMTS5 and MMP-13." (PMID 34769441, 2021).